SLC22A24 (solute carrier family 22 member 24)
Description:
Renal transmembrane organic anion/dicarboxylate exchanger that participates in the reabsorption of conjugated steroids including estradiol-17beta-D-glucuronide (or 17beta-estradiol 17-O-(beta-D-glucuronate)), androstanediol glucuronide (or 5alpha-androstane-3alpha,17beta-diol 3-O-(beta-D-glucuronate)), and estrone 3-sulfate, as well as bile acids taurocholate and glycocholate, driven by an outward gradient of dicarboxylates such as glutarate or succinate. [Isoform 2]: Similar uptake function as Isoform 1. [Isoform 3]: Lack of transporter activity.
Synonyms: MGC34821; NET46
Tractability: Small molecule: it belongs to a druggable protein family. Antibody: UniProt places it where antibodies can reach, with medium confidence; UniProt predicts a signal peptide or a membrane-spanning region; its Gene Ontology location is reachable by antibodies, with medium confidence.
Gene: Protein-coding gene on chromosome 11 (63,077,406 to 63,144,221, reverse strand). Ensembl gene ENSG00000197658.
Subcellular location: Cell membrane (Isoform 1); Cell membrane (Isoform 2)
Gene Ontology:
Molecular function: transmembrane transporter activity
Biological process: steroid metabolic process; sterol transmembrane transport; transmembrane transport
Cellular component: membrane; plasma membrane
Genetic constraint (gnomAD): Loss-of-function variants: 40 observed, 35.1 expected, observed/expected ratio (o/e) 1.14, 90% interval 0.88 to 1.48. The synonymous counts are far from expectation, so gnomAD's model fits this gene poorly and the ratio says little. Missense variants: 703 observed, 574.36 expected, observed/expected ratio (o/e) 1.22, 90% interval 1.15 to 1.3. Synonymous variants: 277 observed, 216.82 expected, observed/expected ratio (o/e) 1.28, 90% interval 1.16 to 1.41.
Homologues: Orthologues: chimpanzee SLC22A24 (98% identical), rabbit SLC22A24 (67% identical), zebrafish oatx (37% identical), zebrafish si:dkey-166k12.1 (30% identical), Drosophila melanogaster Orct (28% identical), Drosophila melanogaster Orct2 (27% identical), zebrafish slc22a4 (27% identical), zebrafish slc22a21 (27% identical), zebrafish slc22a5 (26% identical), Caenorhabditis elegans oct-1 (25% identical), zebrafish si:dkey-119m7.4 (25% identical), Caenorhabditis elegans oct-2 (24% identical), and 43 more. Paralogues in human: SLC22A10 (59% identical), SLC22A25 (57% identical), SLC22A9 (57% identical), SLC22A12 (46% identical), SLC22A11 (44% identical), SLC22A6 (39% identical), SLC22A8 (38% identical), SLC22A7 (32% identical), SLC22A13 (30% identical), SLC22A5 (28% identical), SLC22A3 (28% identical), SLC22A1 (28% identical), and 10 more.
Diseases named in the same sentence as SLC22A24 in open-access papers:
SLC22A24 is named in the same sentence as 11 diseases in open-access papers, as found by Europe PMC text mining. Sharing a sentence is not in itself a finding about the gene and the disease. The quoted sentences say what the papers report.
acne (1 paper, 2019). An inflammatory process of the sebaceous glands which is characterized by comedones, nodules, papules and/or pustules on the skin. "Phenome-wide analysis showed that functional variants of SLC22A24 are associated with human disease such as cardiovascular diseases and acne, which have been linked to dysregulated steroid metabolism." (PMID 31553721, 2019). "Through a detailed search of associations with acne and/or hirsutism, we noted that the top SNPs in the SLC22A24 locus associated with acne (p = 0.001) in the UKBiobank are among the top SNPs significantly associated with steroid and steroid glucuronide levels." (PMID 31553721, 2019).
atherosclerosis (1 paper, 2019). A disease characterized by the build-up of fatty material and calcium deposition in the arterial wall resulting in partial or complete occlusion of the arterial lumen. "In addition to the published data, we used data from the Atherosclerosis Risk in Communities Study (ARIC) to confirm the direction of the association of the nonsense variant, SLC22A24 p.Tyr501Ter, with plasma levels of the two metabolites." (PMID 31553721, 2019).
metastatic tumor (1 paper, 2016). "Expression levels of miR-200a, miR-200b, miR-429, miR-30a-5p, miR-30a-3p, miR-30e, miR-30e-3p, CDH1, SLC22A24, C3orf52 and FREM1 were significantly decreased in metastatic (TNM stage III with pN+ and IV) compared to non-metastatic tumor (TNM stage I and II)." (PMID 27549611, 2016).
osteoporosis (1 paper, 2020). A condition of reduced bone mass, with decreased cortical thickness and a decrease in the number and size of the trabeculae of cancellous bone (but normal chemical composition), resulting in increased fracture incidence. "Yet, a role of this gene region in bone biology cannot be ruled out and needs to be analyzed in studies using cohorts of diagnosed osteoporosis patients, particularly because SLC22A24 had been recently identified as an additional transporter of estrone sulfate." (PMID 33013684, 2020).
tumor (3 papers, 2014 to 2017). "In our study, CDH1 was one of seven EMT-associated genes (CDH1, SCD, PAPSS2, C3orf52, FREM, SLC22A24, SLC25A29) successfully validated to be deregulated in tumor tissue." (PMID 27549611, 2016).
cancer (1 paper, 2016). A tumor composed of atypical neoplastic, often pleomorphic cells that invade other tissues. "We identified other genes (SLC22A24, SLC25A29 and FREM1) as associated with EMT; they were linked to cancer for the first time." (PMID 27549611, 2016).
SLC22A24 also shares sentences with these, for which no sentence is quoted: breast carcinoma (1 paper); cardiovascular diseases (1); conotruncal heart defect (1); Hirsutism (1); ovarian serous cystadenocarcinoma (1).